ANGPTL4 (angiopoietin like 4)
Diseases named in the same sentence as ANGPTL4 in open-access papers (continued):
Sharing a sentence is not in itself a finding about the gene and the disease.
tumor (continued). "Moreover, tumor cells also secrete angiopoietin-like 4 (ANGPTL4) and C-C-chemokine ligand 2 (CCL2), which antagonize endothelial cell tight junctions, promoting tumor cells extravasation." (PMID 39035739, 2024). "Further suggesting that the tumor-suppressive function of ANGPTL4 is via the N-terminus function and is independent of the proangiogenic function of the c-terminus." (PMID 39105498, 2024). "Signal transduction from tumor cells of specific states (stress-like and hypoxia-like tumor cells) to PCs, for example, via the LAMB3/CD44 and ANGPTL4/SDC1 ligand/receptor pairs, was validated by spatial transcriptome analysis and associated with poorer OS as well as nonresponse to immunotherapy." (PMID 37138324, 2023). "MET, GPI, ANGPTL4, HSPA5, TGFA, MIF, and ARTN were significantly up-regulated in tumor samples." (PMID 36447119, 2023). "Furthermore, inhibition of ERK using U0126 partially blocked OA-induced ANGPTL4 expression but dramatically inhibited IL-8 and NOX4 expression, followed by the inhibition of tumor cell invasion." (PMID 37649607, 2023). "Moreover, we ascertained that the different expression of ADRB2, ANGPTL4, BDNF, CBLC, CX3CR1, and IL3RA in tumor and normal group was consistent both in PCR and UALCAN." (PMID 35833114, 2022). "Moreover, the significant downregulation of ANGPT2, ANGPT2, ANGPTL1, ANGPTL4, and ANGPTL6 was found in tumor-adjacent tissues." (PMID 34685578, 2021). "In addition, the elevated ANGPTL4 expression in GCAFs was correlated with tumor differentiation, liver metastasis, venous invasion and Nevin staging, and GBC patients with an elevated ANGPTL4 expression in GACFs were found to have a lower survival rate." (PMID 34331381, 2021). "We demonstrate for the first time that the expression of the genes CA9, NDUFA4L2, EGLN3, BHLHE41, IGFBP3, and ANGPTL4, regulated by HIF1, is largely correlated, and along with VWF, the expression levels of these genes during tumor progression decreased coordinately." (PMID 34046336, 2021). "The present study aimed to investigate the molecular mechanisms by which ANGPTL4 expression might regulate epithelial-mesenchymal transition (EMT) and the tumor microenvironment in CRC." (PMID 34405010, 2021). "The results revealed that hypoxia stimulated cells to synthesize EVs proteins involved in enhancing tumour cell proliferation (NRSN2, WISP2, SPRX1, LCK), metastasis (GOLM1, STC1, MGAT5B), stemness (STC1, TMEM59), angiogenesis (ANGPTL4), and suppressing host immunity (CD70)." (PMID 33050615, 2020). "Furthermore, depletion of NOX4, ANGPTL4, MMP-1, and MMP-9 in CRC cells significantly blocked OA-enhanced metastatic seeding of tumor cells in lungs." (PMID 32641980, 2020). "However, TGF-β2 is only partially responsible for the ANGPTL4 induction by ACM, as tumor cell ANGPTL4 induction in the full ACM was about 1.6-fold compared with that in the TGF-β2-depleted ACM, whereas it was about threefold compared with that in DMEM." (PMID 31602400, 2019). "In contrast to ANGPTL4, which was extensively studied in various types of cancers, Sp4 expression in tumor specimens has never been evaluated." (PMID 31717924, 2019). "As expected, ANGPTL4 inhibitor could strikingly decreased the proliferation of GCT, as well as the tumor volume in xx model." (PMID 28903395, 2017). "In order to figure out whether a high level of TGF-β induces the up-regulation of ANGPTL4 in GCT, we firstly performed the immunolocalization of TGF-β in human specimens of GCT and para-tumor normal bone tissues." (PMID 28903395, 2017). "The results indicated that ANGPTL4 knock down in MBM cells does not affect these tumor cells migratory and invasion ability." (PMID 29100268, 2017). "In ER negative breast tumors, TGFβ induces ANGPTL4 expression, thereby priming tumor cells for lung metastasis." (PMID 29100268, 2017).
tumor (continued). "Although a role for ANGPTL4 in promoting tumor cell intravasation has not been explored, ANGPTL4 also plays an important role in promoting vascular permeability of retinal vessels in ischemic retinal disease." (PMID 26761211, 2016). "Genes that enable tumor cells to extravasate and survive at the secondary tissue site contribute to metastasis progression including prostaglandin G/H synthase 2 (PTGS2), epiregulin, and angiopoietin-like 4 (ANGPTL4)." (PMID 27600078, 2016). "Similarly, in the older patients, ANGPTL4, MYBL2 and VEGFA, all maintained significance after correcting for subtype and tumor grade in multivariate analysis (Multivariate Model)." (PMID 25999348, 2015). "The copy number of ANGPTL4 gene in tumor tissues was significantly lower than in non-tumor tissues of HCC patients." (PMID 25148701, 2014). "In our study, the overall expression level of ANGPTL4 mRNA in tumor tissues of HCC patients was lower than non-tumor tissues and healthy liver tissues." (PMID 25148701, 2014). "The result from pyrosequencing showed that there were 5 to 20% of positive methylations detected among the 5 CpG sites of the ANGPTL4 promoter in tumor tissues while there was no positive methylation detected in all non-tumor tissues." (PMID 25148701, 2014). "Higher frequency of methylation of CpG sites of ANGPTL4 promoter was detected in tumor tissues compared to non-tumor tissues." (PMID 25148701, 2014). "Most importantly, ANGPTL4 treatment could suppress HCC progression and metastasis through promotion of tumor apoptosis, inhibition of tumor motility and angiogenesis, and disruption of tumor-favorable microenvironment." (PMID 25148701, 2014). "ANGPTL4 mRNA levels in tumor and non-tumor liver tissues of HCC patients were analyzed to investigate its clinical relevance." (PMID 25148701, 2014). "The average expression level (log2 base) of ANGPTL4 mRNA among tumor, non-tumor and healthy donor liver tissues were 5.98, 7.13 and 6.98 respectively." (PMID 25148701, 2014). "Therefore, we supposed that upregulation of ANGPTL4 in ESCC was an adaptive response to tumor microenvironment, which in turn influence tumor development." (PMID 23925665, 2013). "Angiopoietin-like 4 (ANGPTL4, NM_016109), which increases triglycerides by potent inhibition of lipoprotein lipase, was increased in ccRCC tumor tissue by 23-fold and may play a major role in lipid accumulation." (PMID 20502531, 2010). "Previous studies have shown that secreted ANGPTL4 interacts with integrin β1 and β5 on the cell surface, triggering downstream signaling pathways such as focal adhesion kinase (FAK) and proto-oncogene tyrosine-protein kinase SRC, thereby affecting tumor progression." (PMID 39910592, 2025). "Moreover, normal prostate tissue does not express ANGPTL4, and its positive expression—when combined with tumor stage—serves as an indicator of PSA recurrence following surgery." (PMID 40723247, 2025). "Therefore, tumor cells destroy the normal connection of vascular endothelium by secreting protein angiopoietin-like 4 (Angptl4) and various cytokines, such as cyclooxygenase-2 (COX-2), epiregulin (EREG), and MMP-1/2, thereby promoting the extravasation of tumor cells." (PMID 40356596, 2025). "Thus, we investigated whether tumor cell expression at the invasive front of the proteins CD36, FABP4, and ANGPTL4, which are involved in the release, cellular uptake, and transport of fatty acids differs between normal and overweight/obese TNBC patients." (PMID 39456610, 2024). "In addition, we found that these ligands secreted by hypoxia-related GBM cell types, namely, MES1-like tumor cells, MES2-like tumor cells, and TAM-1, may stimulate angiogenesis via, for example, ADM, ANGPTL4, GDF15, and VEGFA." (PMID 35669791, 2022). "However, the mechanism of radioresistance of NSCLC mediated by hypoxic tumour cell-derived exosomal ANGPTL4 had not been studied yet." (PMID 36050447, 2022).
tumor (continued). "Whether the increased expression of pro-angiogenic factors (e.g. VEGFA, ANGPTL4) is involved in mediating tumor progression was not investigated." (PMID 36074318, 2022). "At the initial stage of tumor development, the activation of the genes under consideration provides adaptation to hypoxia, accompanied by a metabolic shift, i.e., the development of glycolysis and a decrease in oxidative phosphorylation (EGLN3, NDUFA4L2, ANGPTL4, CA9, and, apparently, IGFBP3)." (PMID 34046336, 2021). "Several of these HSEPs have been reported in other contexts to play key roles in tumour progression by cancer cell proliferation (NRSN2, WISP2, SPRX1, LCK), metastasis (GOLM1, STC1, MGAT5B), and stemness (STC1, TMEM59), as well as promoting angiogenesis (ANGPTL4) and host immunosuppression (CD70)." (PMID 33050615, 2020). "Transcriptome analysis of sorted MC-38 tumor cells revealed upregulation of vessel-stabilizing factors such as endostatin, Pdgfa, Thbs2 in HIF-1α-KD cells and reduced expression of pro-angiogenic factors such as Cyr61, Cox-2 and Angptl4 when compared to Mock tumors." (PMID 33142239, 2020). "However, in 161 TNBC patients, the ANGPTL4 expression level was not correlated with age, menstrual history, tumor stage or other clinical factors." (PMID 32928141, 2020). "Considering the pro-tumourigenic effects of HIF in these cancers, ANGPTL4 might be expected to also exert tumour-promoting effects, but this has not been investigated." (PMID 28458654, 2017). "Moreover, the knockout of ANGPTL4 could significantly attenuate the effect of GCTSC proliferation and tumor angiogenesis." (PMID 28903395, 2017). "To determine whether ANGPTL4 was expressed in UM cells in vivo, we performed orthotopic (intraocular) transplantation using the OCM1 cell line and observed uniform expression of ANGPTL4 in tumor cells, similar to the expression of VEGF." (PMID 26761211, 2016). "In addition, RT-qPCR analysis from mice biopsies indicated that the expression by tumor cells of CXCR4 and ANGPTL4, two TGF-β target genes identified as key players to prime cancer cells towards the lungs, were both reduced when mice were treated with halofuginone." (PMID 26015407, 2015). "In this study, Ad-ANGPTL4 treatment significantly suppressed the formation of new vessels in the tumor through repressing the expression of angiogenic factor VEGF and suppressing the activation of Raf-MEK-Erk signaling pathway, suggesting an anti-angiogenic effect of ANGPTL4 on HCC." (PMID 25148701, 2014). "However, a recent study demonstrated that the expression levels of ANGPTL4 protein in tumor tissues are significantly lower than in non-tumor tissues of HCC patients." (PMID 25148701, 2014). "The tumor tissues expressed a 2.2-fold lower level of ANGPTL4 mRNA than non-tumor tissues of HCC patients in average, which was statistically significant using unpaired and paired t-tests (2-tailed unpaired t-test, p < 0.0001; 2-tailed paired t-test, p < 0.0001)." (PMID 25148701, 2014). "ANGPTL4-786 also failed to change the tumor growth by VHL-/- cells significantly." (PMID 24260413, 2013). "More recently, ANGPTL4 was shown to bind and inhibit lipoprotein lipase, a function consistent with the cachexia induced by tumors, where a reduction of fatty acid incorporation into fat cells serves the energy needs of the tumor rather than the host." (PMID 15836779, 2005). "Furthermore, ANGPTL4 has been observed to enhance the pro-survival intracellular oxygen to H2O2 ratio, leading to anoikis (anchorage independent growth of cells-feature of cancer cells) resistance in tumors and promoting tumor-growth via the PI3K/PKBα/ERK signaling pathway." (PMID 39811640, 2025). "However, this tumor suppressive function of ANGPTL4 is not observed in all ccRCC cells." (PMID 39105498, 2024).
tumor (continued). "Knockout of ANGPTL4 in 786O cells which have mutant VHL, significantly reduced tumor growth as did treatment with anti-cANGPTL4 antibodies, suggesting that in 786O cells, the proangiogenic tumor-promoting function of cANGPTL4 may be predominant over the tumor suppressive function." (PMID 39105498, 2024). "However, we found low ANGPTL4 expression in the tissue, which was also validated in the additional sample GSM5224029, suggesting that ANGPTL4 may be secreted only by some specific tumor cells." (PMID 37138324, 2023). "Therefore, the upregulation of CCL21 and ANGPTL4 in this trial might favor more aggressive disease and not necessarily benefit tumor suppression." (PMID 37688629, 2023). "However, not in every tumor type, ANGPTL4 promotes tumor progression." (PMID 36074318, 2022). "Similarly, hypoxia induced the upregulation of angiopoietin-like 4 (ANGPTL4), HIF-1α/COX-2 and miR-135b and miR-210 in the exosome cargo of A549 cells, exosome transfer of these factors to other A549 cells led to the enhanced proliferation, migration, angiogenesis, and tumor progression." (PMID 35444652, 2022). "However, studies on the role of ANGPTL4 in tumour radioresistance are hitherto lacking." (PMID 36050447, 2022). "However, this does not prove that ANGPTL4 is a tumor suppressor gene." (PMID 36553482, 2022). "In the present case, treatment with RA may lead to differentiation of tumor cells rendering them less aggressive but induction of resistance genes such IL-8, HILDPA, IGFBPA, and ANGPTL4 may have a negative impact on the neoplastic process causing stimulation of angiogenesis and further progression." (PMID 26362268, 2015). "Thus, serum ANGPTL4 may not be exclusively secreted by tumor cells, and its application in clinic needs further study." (PMID 23925665, 2013). "Related to this, in this study, ANGPTL4 expression in CCA tissues correlated with lymph node metastasis and tumor stage but did not correlate with vascular invasion." (PMID 35392474, 2022). "Using multiple logistic regression analysis, all clinicopathological parameters, including tumor size, lymph node status, ER and PR status, HER2 expression, and molecular subtype, failed to predict the expression of ANGPTL4." (PMID 35366286, 2022). "There were no studies of ANGPTL4, CRABP1, MET, and SEMA3A in Oncomine, but in UALCAN, they were frequently expressed in tumor group than normal tissues." (PMID 35833114, 2022). "The concentration of ANGPTL-4 was not modified by the tumor stage in WSC group (p= 0.89), CC group (0.07) and between I-II and III-IV tumor stage (p=0.09)." (PMID 31741709, 2019). "The same authors demonstrated that cANGPTL4, and not full-length ANGPTL4 or nANGPTL4, increased CRC cell proliferation and tumor growth both in vitro and in vivo." (PMID 29389861, 2018). "Of note, inhibition of both ANGPTL4 and VEGF expression by RNAi was not sufficient to completely abolish the angiogenic potential of UM tumor cells in vitro." (PMID 26761211, 2016). "We further discovered that the lack of ANGPTL4, EGLN3 or ENO2 expression did not change tumor growth." (PMID 24260413, 2013). "Thus, increased lipase activity within the tumor and elevated CD36 expression favors lipid mobilization and utilization in the tumor-EC compartment when endothelial Angptl4 is absent." (PMID 38086791, 2023). "Comparing paired tumor and non-tumor tissues of each HCC patients, 51.82% (57/110) of tumor tissues were found to have lower expression of ANGPTL4 mRNA while 16.36% (18/110) of tumor tissues expressed higher ANGPTL4 mRNA." (PMID 25148701, 2014).
cancer (195 papers, 2008 to 2026). A tumor composed of atypical neoplastic, often pleomorphic cells that invade other tissues. "Hypoxia, in particular through the HIF1A transcription factor, was implicated in the expression of ANGPTL4 in cancer cells, in presumably non‐senescence contexts." (PMID 41347893, 2026). "Activation of the STAT3 pathway in cancer-associated fibroblasts leads to elevated secretion of ANGPTL4, which is associated with shorter survival in patients." (PMID 39910592, 2025). "ANGPTL4, a notably significant marker, has been extensively reported to be associated with fibroblast function and cancer progression." (PMID 40340806, 2025). "Interleukin 6 (IL-6), enriched in cancer-associated adipocytes, and lipolysis-derived free fatty acids (FFAs) released from adipocytes, amplify ANGPTL4-mediated glycolysis and metastasis through activation of STAT3 and PPARα pathways in TNBC cells." (PMID 40616161, 2025). "Mechanistically, cancer-associated adipocytes (CAAs) secrete IL-6 and release free fatty acids (FFAs), which serve as metabolic sensors to activate ANGPTL4 via STAT3 and PPARα signaling pathways in TNBC cells." (PMID 40616161, 2025). "This includes an analysis of prognostic outcomes, clinicopathological data, mutational burden, and genomic information to elucidate ANGPTL4’s central role across various cancer types." (PMID 40233044, 2025). "Consistently, previous studies have established that STAT3 activation is responsible for ANGPTL4 expression in cancer-associated fibroblasts (CAFs)." (PMID 40616161, 2025). "The liver secretes cleaved ANGPTL4 (cANGPTL4), the most potent version of this gene product that has been linked to cancer metastasis." (PMID 39796157, 2024). "A recent study revealed that the trafficking and secretion of ANGPTL4 via vesicle-associated actin assembly mediated by TGF-β is important for cancer development." (PMID 38643448, 2024). "This is perhaps not surprising given a rather large body of literature describing not only ANGPTL4’s role in cancer but also cardiovascular disease risk and metabolism." (PMID 37291514, 2023). "DNA methylation-mediated silencing of ANGPTL4 induces the activation of cancer-associated fibroblasts (CAFs) and help CRC transfer through the ERK pathway, enhancing its invasive ability." (PMID 36447119, 2023). "ANGPTL4 is a secreted protein that has been implicated in multiple physiopathologic processes, including lipid metabolism, and cancer progression." (PMID 38159259, 2023). "Angiopoietin-like protein 4 (ANGPTL4) is induced by hypoxia, and its high expression is associated with progression and poor prognosis in several types of cancers." (PMID 36497250, 2022). "ANGPTL4 is associated with a poor prognosis of patients with various solid tumors, suggesting an important role in cancer onset and progression." (PMID 34680556, 2021). "Further evidence has demonstrated that ANGPTL4 can be a potential diagnostic or prognostic marker for numerous cancers." (PMID 31963541, 2020). "Several studies showed that high levels of ANGPTL4 are associated with poor prognosis in patients with various solid tumors, suggesting an important role in cancer onset and progression, metastasis, and anoikis resistance." (PMID 28182091, 2017). "Angptl4, Cxcl12 and Mdk, which are upregulated in our model, have all been implicated in cancer development and progression." (PMID 24039874, 2013). "ANGPTL4 deficiency in cancer cells also abolished the tumorigenic abilities of these cells in athymic nude mice." (PMID 22481923, 2012). "We show that increased ANGPTL4 expression is associated with CAF infiltration in 21 different cancer types, elucidating that ANGPTL4 expression is a strong predictor of CAF infiltration, and providing another explanation to why TME expression of ANGPTL4 correlates to poor prognosis." (PMID 40233044, 2025).